DCLK1 (doublecortin like kinase 1)
Diseases named in the same sentence as DCLK1 in open-access papers (continued):
Sharing a sentence is not in itself a finding about the gene and the disease.
colorectal cancer (continued). "DCLK1 regulates the EMT process in pancreatic, liver, kidney, and colorectal cancers; knockdown of DCLK1 results in decreased cancer growth, EMT, and metastasis." (PMID 27335684, 2016). "Doublecortin-like kinase 1 (DCLK1) marks TSCs in pancreatic and colorectal cancer and regulates EMT and stemness." (PMID 25605241, 2015). "Doublecortin-like kinase 1 (Dclk1) is overexpressed in many cancers including colorectal cancer (CRC) and it specifically marks intestinal tumor stem cells." (PMID 25211188, 2014). "In pancreatic and colorectal cancer cells, we have previously demonstrated that DCLK1 negatively regulates miRNA let-7a." (PMID 24040120, 2013). "Similarly, in vitro experiments using colorectal cancer lines reveal that silencing DCLK1 increases radiosensitivity at doses around 6 Gy, underscoring DCLK1’s function in DNA repair and cell survival signaling after moderate IR exposure." (PMID 40563698, 2025). "Of note, we also observed the regulation of DCLK1 by miR-124-3p, possibly due to the indirect regulatory effect of miR-124-3p on DCLK1 gene expression since miR-124-3p has multiple target genes and exhibits tumor suppressive effect in colorectal cancer." (PMID 36210463, 2022). "Therefore, the current systematic review and meta-analysis aimed to review the available in vitro, in vivo, and clinical evidence on the oncogenic roles and clinical significance of DCLK1 isoforms in colorectal cancer." (PMID 35717205, 2022). "For example, DCLK1 was found up-regulated in renal clear cell cancer and colorectal cancer." (PMID 36569325, 2022). "In the mouse intestinal polyps, DCLK1+ cells in part co-express other stem-cell-associated markers, such as CD44, LGR5 and CD133; furthermore, DCLK1+ cells have been observed in human colorectal cancers." (PMID 29652830, 2018). "Importantly, in some colorectal cancer models, the silencing of the expression of DCLK1 inhibited the invasion and metastasis by tumor cells." (PMID 29652830, 2018). "Interestingly, colorectal cancer with high DCLK1 expression had increased cancer specific mortality." (PMID 26621833, 2016). "Recent studies have shown that DCLK1 is highly expressed in gastrointestinal stem cells and it marks tumor stem cells that produce tumor progeny in the polyps of Apc (Min/+) mice, suggesting an important function for DCLK1 in colorectal cancer as well." (PMID 24086625, 2013). "Finally, we noted increased DCLK1 expression in association with Wnt/β-catenin signaling in human tubular adenomas and invasive colorectal cancers, but not normal colon tissue." (PMID 29254234, 2017). "In contrast we observed that DCLK1 and FGF19 were colocalized in both colorectal cancer and NAT tissues supporting a role for their interaction in colon cancers but not PDAC." (PMID 40162222, 2025). "The main targets for CAR T cell therapy in colorectal cancer include CEA, MSLN, Guanylyl Cyclase C (GUCY2C), EpCAM, HER2, and Doublecortin-like kinase 1(DCLK1)." (PMID 38622705, 2024). "We chose to evaluate the effects of the DCLK1 CAR-T in LoVo cells, because this colorectal cancer cell line is derived from the distant metastatic lesion of a 56-year old patient with a histologically confirmed adenocarcinoma of the colon." (PMID 31878090, 2019). "DCLK1 (doublecortin-like kinase 1), a CSC marker for intestinal and adenoma cancer, has been recently identified as an epigenetic biomarker of colorectal cancer which is regulated by promoter methylation." (PMID 31320814, 2019). "Dclk1, a colorectal CSC marker, is strongly expressed in E. faecalis-triggered colorectal cancer and allograft tumors derived from YAMC cells treated by commensal-infected macrophages or purified 4-HNE." (PMID 29254234, 2017). "More recent studies have also defined transcription factors DCLK1 and LGR5 to play a significant role in quiescent and active stem cells in colorectal cancer." (PMID 27668882, 2016).
colorectal cancer (continued). "This study demonstrates that Dclk1 is critically involved in facilitating intestinal tumorigenesis by enhancing pluripotency and EMT factors in Apc mutant intestinal tumors and it also provides a potential therapeutic target for the treatment of colorectal cancer." (PMID 25211188, 2014). "The remaining investigated CSC markers (DCLK1, ANXA2, and CD44) did not demonstrate a statistically significant relationship with tested clinicopathological features of colorectal cancer." (PMID 32671503, 2020).
colon cancer (46 papers, 2013 to 2025). "These analyses of patient colon cancer tissues provide clinical support for our finding that Foxy5 treatment of mice with colon cancer xenografts caused a reduction in DCLK1 mRNA." (PMID 37998393, 2023). "DCLK1 is a microtubule-associated protein in which its expression has been reported to be critically required for maintaining the growth of human colon cancer cells." (PMID 34268251, 2021). "In another study, quiescent Dclk1+ tuft cells served as colon cancer-initiating cells following loss of Apc and in the presence of inflammation in a Dclk1CreErt mouse model." (PMID 31878090, 2019). "Lineage-tracing experiments using Dclk1-driven Cre recombinase mouse models demonstrate that the Dclk1+ tuft cell is a cell of origin for adenomas and colon cancer following loss of Apc in the intestine." (PMID 25605241, 2015). "Analysis of RNA deep-sequencing data from the cancer genome atlas colon cancer dataset revealed that DCLK1 transcript variant 1, which encodes isoform 1 (also known as DCLK-short-α), is the most highly expressed annotated variant." (PMID 24885928, 2014). "In colon cancer models, autophagy inhibition causes p62 to accumulate and co-localize with DCLK1 in autophagosomes of murine and human tumors and is associated with preventing DCLK1 degradation and increased DCLK1 isoform promoter activity." (PMID 40563698, 2025). "The loss of Dclk1 in our tumor models might reflect the disturbed differentiation in the colon tumors and the relatively high Wnt signaling level in Apc LOF mice." (PMID 27811361, 2016). "Doublecortin-like kinase 1 (Dclk1), a microtubule-associated kinase, marks the fifth lineage of intestinal epithelial cells called tuft cells that function as tumor stem cells in Apc mutant models of colon cancer." (PMID 26285154, 2015). "However, DCLK1+ cells are able to generate colon cancers when APC loss was followed by an inflammatory stimulus such as colitis: the effect of the inflammatory stimulus was active in inducing tumorigenesis when both were given immediately after APC loss or after three months." (PMID 29652830, 2018). "DCLK1 expression was negatively correlated with WNT5A expression in colon cancer cohorts and was experimentally reduced by WNT5A signaling." (PMID 37998393, 2023). "The DCLK1 locus shows methylation of the cytosines in CpG islands overlapping the alpha promoter in multiple cancers, including colon cancers." (PMID 38003596, 2023). "Next, we investigated the predictive value of combining the mRNA expression levels (low and high) of WNT5A and DCLK1 in colon cancer tissues and then correlated the expression profiles with the overall survival of the patients." (PMID 37998393, 2023). "To confirm that LGR5 and DCLK1 are both colon cancer stem cell markers and are related to WNT5A signaling, we studied colony and spheroid formation of colon cancer cells, assays used to demonstrate the presence of cancer stem cells." (PMID 37998393, 2023). "Univariate analysis revealed that patients expressing high levels of DCLK1 in their colon cancer tissues had a significantly (p < 0.01) worse prognosis than patients with low DCLK1 expression in their cancer tissues." (PMID 37998393, 2023). "In the smaller Malmö-CC cohort used for IHC analysis of protein expression, we found that colon cancer tissue expressed significantly higher DCLK1 protein levels than matched normal mucosa." (PMID 37998393, 2023). "To fully evaluate such a possible inconsistency between the cancer stem cell markers LGR5 and DCLK1, we also investigated the expression and prognostic value of DCLK1 in the two colon cancer cohorts and how it correlated with WNT5A expression." (PMID 37998393, 2023). "The discovery of DCLK1 potentials to distinguish colorectal CSCs from normal stem cells in CRC highlighted DCLK1 as a colon cancer-specific marker." (PMID 35717205, 2022).
colon cancer (continued). "DCLK1 has been detected in cancer stem cells (CSCs) from esophageal, pancreatic, and colon cancers, suggesting that CSCs are derived from malignant TCs." (PMID 36704202, 2022). "Prior studies using DCLK1-IN-1 treatment in pancreatic and colon cancer cell lines demonstrated that it has a limited ability to inhibit proliferation and colony formation in 2D cell cultures." (PMID 34830884, 2021). "MiR-137 can also regulate the tumorigenicity of colon cancer stem cells through the inhibition of DCLK1." (PMID 32433716, 2020). "The mRNA expression levels of the colon cancer-specific stemness markers DCLK1, LGR5, and ALDH1A1 were elevated in HT-29 as well as in Caco-2 cell-derived colonospheres and were downregulated after LTC4 stimulation." (PMID 32814764, 2020). "Here we have shown that γ-Mangostin decreases expression of both LGR5 and DCLK1 in colon cancer cells along with inhibition of colonosphere formation." (PMID 31608135, 2019). "As proof of concept, we utilized two validated colon cancer cell lines to confirm Dclk1's co-localization with p62." (PMID 31040926, 2019). "DCLK1 mRNA was highly expressed in colon cancer stem cells but expressed only at low levels in normal intestinal stem cells." (PMID 29652830, 2018). "With these important targets of miR-15a, (BCL2, BMI1, YAP1 and DCLK1) in colon cancer having potential to promote colon cancer growth, we investigated the effects of miR-15a on cell proliferation." (PMID 29416778, 2018). "DCLK1+ cells were widely distributed in colon cancer specimens, while DCLK1-positive epithelial cells are rarely detected in normal colon tissue." (PMID 29652830, 2018). "Blocking β-catenin/TCF4 signaling using FH535 and CTNNB1-specific small interfering RNA decreased DCLK1 expression in HCT116 human colon cancer cells." (PMID 29254234, 2017). "Long-lived DCLK1+ tuft cells were also involved in regeneration upon chemical or microbial-induced injury and likely contributed to colon cancer as a tumor-initiating population with persistent Wnt activation." (PMID 28757546, 2017). "In fact, a recent study showed that Dclk1 is silenced in human colon cancer by promoter methylation." (PMID 27811361, 2016). "Recently, DCLK1 methylation has been reported as a biomarker in cholangiocarcinoma and colon cancer." (PMID 25605241, 2015). "DCLK1 is also overexpressed in the Apcmin/+ mouse model of intestinal neoplasia and surgical specimens of human colon cancer." (PMID 24885928, 2014). "However, in a cancer more affiliated with inflammation we found that the colocalization of DCLK1 and pGSN in colon cancer was more abundant." (PMID 40162222, 2025). "As such, dedifferentiation of committed (secretory) lineages may lie upstream of DCLK1 activation in colon cancer and characterize a subset of patients eligible for immune therapy." (PMID 36711533, 2023). "Furthermore, immunofluorescence was performed with PUM1 and some colon cancer stems markers such as DCLK1 and CD133." (PMID 37624174, 2023). "DCLK1 expression was similar in left-sided and right-sided colon cancer." (PMID 31979136, 2020). "These functional roles in the TME may be specific to left-sided subtypes in colon cancer and DCLK1 may have potential as a prognostic biomarker and adjuvant target to promote immunotherapy sensitivity to improve outcomes in colon and gastric cancer patients." (PMID 31979136, 2020). "Interestingly, expression of DCLK1 has been widely detected in clinical colon cancer specimen while DCLK1-positive cells in normal colon tissue are very rare." (PMID 31530793, 2019). "Finally, staining of the surgically resected tumors from patients with colon cancer and metastasis to the liver clearly demonstrated co-localization of p62/Dclk1 puncta both at the plasma membrane and within the nucleus suggesting involvement of both isoforms." (PMID 31040926, 2019).
colon cancer (continued). "Furthermore, studies carried out with human colon cancer stem cells support a key role for DCLK1 in maintaining tumor sphere growth in vitro and in vivo." (PMID 29652830, 2018). "Recent studies also demonstrated that DCLK1 distinguishes between tumor and normal stem cells in the intestine and could be a therapeutic target for colon cancer." (PMID 26673007, 2016). "Recent studies demonstrated that DCLK1 distinguishes between tumor and normal stem cells in the intestine and could be a therapeutic target for colon cancer." (PMID 26673007, 2016). "Thus the literature so far strongly implicates a possible important role of DCLK1 in mouse colon tumorogenesis and in maintaining the growth of human colon cancers." (PMID 26447334, 2015). "A clinically important discovery of the current studies is that an alternate-promoter (β) within IntronV of DCLK1 gene is used by human colon cancer cell lines (hCCCs) and hCRCs to express a short-transcript of DCLK1 (DCLK1-S) (termed Isoform 2 in NCBI data base)." (PMID 26447334, 2015). "Our laboratory has focused on DCLK1, a calmodulin-like kinase not only because it was originally identified to mark quiescent stem cells in the normal intestine, but also that it is a marker for colon cancer stem cells." (PMID 23533514, 2013). "Thus, tuft cells may serve as a novel choice in the treatment of colon cancer by targeting DCLK1-positive cancer stem cells." (PMID 36569325, 2022). "Yet, whether it directly contributes towards tumor growth and progression is being elucidated in colon-specific Dclk1 knockouts as they are being bred to ApcMin/+ mice to definitively link Dclk1 in colon cancer development and progression in response to CR infection." (PMID 31040926, 2019). "Thus, co-localization of p62 with Dclk1 may hamper Dclk1's elimination to impact colon cancer development and progression." (PMID 31040926, 2019). "Although these findings are interesting and offer therapeutic potentialities, future studies are required to assess whether DCLK1 marks cancer stem cells in primary human colon cancers and whether this marker really englobes the whole tumoral cell population endowed with tumor-initiating capacities." (PMID 29652830, 2018). "Since β-catenin signaling promotes colon cancer stemness, we explored how WNT5A expression is related to that of the cancer stem cell marker DCLK1." (PMID 37998393, 2023). "Drug treatment also reduced PUM1 expression and cancer stem cell marker (DCLK1 and CD133) expression in colon cancer cells." (PMID 37624174, 2023). "There are several possible explanations for such discrepancies, including different isoforms of DCLK1, the plasticity of LGR5 expression and the presence of different subpopulations of colon cancer stem cells." (PMID 37998393, 2023). "This was also confirmed in vivo, where HNK treatment significantly reduced the expression of DCLK1 and LGR5 in the colonic tumors." (PMID 34206989, 2021). "We further provide evidence of p62/Dclk1 interaction in AOM/DSS and BLT1−/−;ApcMin/+ models of colon cancer as well as in surgical samples of a colon cancer patient with liver metastasis." (PMID 31040926, 2019). "AOM/DSS treatment of Apc1638N/+ mice phenocopied CR+AOM treatment as colonic tumors exhibited pronounced changes in Ki-67, EZH2 and Dclk1 accompanied by infiltration of F4/80+ macrophages, CD3+ lymphocytes and CD3/β-catenin co-localization." (PMID 31040926, 2019). "In tumors from CR-infected, CR+AOM or AOM/DSS-treated Apc1638N/+ mice and surgically-resected colon tumor/metastatic liver samples, significant accumulation of p62 and it's co-localization with LC3B and Dclk1 was evident." (PMID 31040926, 2019). "Several important colon cancer related genes, including well established targets of miR-15a, BCL2 and BMI1 as well as novel targets, YAP1 and DCLK1 contain binding sites for miR-15a in their 3’UTRs." (PMID 29416778, 2018).
colon cancer (continued). "Based on these results, we next performed an analysis and found a strong negative correlation (R = −0.56) between WNT5A and DCLK1 gene transcript expression in the GSE44076 colon cancer cohort." (PMID 37998393, 2023). "Furthermore, according to recent evidence, doublecortin-like kinase 1 (DCLK1)-targeted CAR-T cells effectively eradicate primary and metastatic colon cancer cells, rendering DCLK1 a promising target for future endeavors." (PMID 36564524, 2023). "DCLK1 contributes to the promotion of EMT by means of the overexpression of mesenchymal markers (Vimentin) and transcriptional regulators (ZEB1) and the downregulation of the epithelial marker E-cadherin in colon cancer cells." (PMID 35717205, 2022). "The ablation of DCLK1 in colon cancer CSC only restored the cell death-promoting effects mediated by curcumin, highlighting that curcumin-mediated autophagy is dependent on the expression of DCLK1." (PMID 34299604, 2021). "DCLK1, the transcription factor, is regulated by Wnt signaling through the LEF-binding site at its promoter region and has been shown to be enriched in metastatic liver and colon cancers." (PMID 28757546, 2017). "Unlike the neuronal cells, possible expression of different isoforms of DCLK1 by normal colonic epithelial cells and colon cancer cells/tumors has not been investigated to-date." (PMID 26447334, 2015). "Similarly, in the context of further DSS-induced inflammation, Apc deletion in DCLK1+ TCs resulted in the development of colon tumors, whereas no DCLK1-expressing cells developed tumors in the steady state." (PMID 36704202, 2022). "Preliminary investigations (data not shown) revealed that candidate markers differentially expressed between PC- and Lgr5+-initiated mouse tumors such as DCLK1 and HOXB9 were not equally discriminative among patient-derived colon cancers." (PMID 38902475, 2024).